CRP (C-reactive protein)
Diseases named in the same sentence as CRP in open-access papers (continued):
Sharing a sentence is not in itself a finding about the gene and the disease.
septic shock (74 papers, 2006 to 2026). Shock caused by infection; frequently caused by gram negative bacteria, although some cases have been caused by other bacteria, viruses, fungi, and protozoa; characterized by fever, chills, tachycardia, tachypnea, and hypotension. "Among patients with septic shock, serum lactate levels showed moderate diagnostic accuracy for predicting patient intubation (AUC = 0.745, cut-off = 2.95, (0.641, 0.286)); while C-reactive protein and serum lactate exhibited low diagnostic accuracy (i.e., 0.718 and 0.666, respectively)." (PMID 38576552, 2024). "In clinical practice, KDSS is often misdiagnosed as septic shock, as both conditions present with peripheral circulatory dysfunction, hypotension, elevated CRP and increased interleukin‐10 (IL‐10)." (PMID 41055207, 2026). "Overall, blood routine (neutrophils, lymphocytes, and monocytes) and infection biomarkers (C-reactive protein, serum ferritin, and procalcitonin) were significantly different between septic shock patients and healthy controls." (PMID 36845110, 2023). "In septic shock patients, neutrophil counts, infection biomarkers (C-reactive protein, ferritin, and procalcitonin levels), and cytokines (IL-1β, IL-2R, IL-6, IL-8, IL-10, and TNF-α) increased significantly." (PMID 36845110, 2023). "•Septic shock group showed lower TG, HDLc, monocytes and M/H ratio and higher CRP, IL-6, IL-8 and IL-10 levels at admission." (PMID 36368184, 2022). "In model 3 with the maximum covariates including age, sex, APACHE II score, PaO2/FIO2,vasopressor use, CRRT, CKD, AKI, septic shock, albumin, creatinine, leukocyte, and CRP, adjusted HR for in-hospital mortality was 2.640 (95%CI, 1.208–5.767,P = 0.015)." (PMID 36115956, 2022). "The septic shock group (n = 22) revealed a higher number of male subjects, CRP, IL-6, IL-8 and IL-10 levels, while lower TG, HDLc, monocyte numbers and M/H ratio at admission compared to the non-shock group (n = 27)." (PMID 36368184, 2022). "Then, 24–48 h after a peak in CRP levels, a decrease was observed, which corresponds to a response to the initiation of a comprehensive treatment of septic shock." (PMID 35453325, 2022). "In the univariable Cox proportional hazards model, VIS 16–30, VIS 31–45, VIS > 45, age, SOFA scores, septic shock, initial lactate levels, CRP levels, procalcitonin levels, fluid at 3 h, and fluid at 6 h appeared to be related with a p-value of <0.2." (PMID 33572578, 2021). "Of the 2,264 eligible patients in the Korean Shock Society (KoSS) septic shock registry, we excluded 124 patients due to missing 28-day mortality data and 367 patients due to missing CRP or PCT data." (PMID 31036824, 2019). "One study observed an increase in the mean arterial pressure, cardiac index, systemic venous resistance index, and a 72% decline in CRP in patients with septic shock treated with CPFA." (PMID 24350088, 2013). "For the prediction of septic shock the AUROC was 0.73 for CRP, 0.85 for PCT and 0.76 for ICIS." (PMID 27384242, 2016). "For predicting ICU, hospital, and 30-day mortality rates after hospital discharge, we included APACHE II score on admission, age, reasons for ICU admission, NIV and IMV implications, presence of septic shock, CRP level, and previous HRLD use in the binary logistic regression model." (PMID 24495706, 2014). "A subsequent study by the same group demonstrated that combining PSP with CRP and PCT further improved predictive accuracy for mortality in ICU patients with septic shock." (PMID 40863214, 2025). "GCS, SOFA score, APACHE 2 score, lactate, CRP, procalcitonin, PRO-ADM, IL-6, CD64 level and 28-day mortality were evaluated in patients with septic shock followed-up in the intensive care unit of Marmara University Hospital between July 2021 and December 2021." (PMID 37592204, 2023).
septic shock (continued). "In the validation cohort, clinical inflammatory parameter CRP was similar in the septic (median: 270.0, Interquartile range (IQR): 247.0) and septic shock groups (median: 235.0, IQR: 179.0), but was higher than in the CIP group (median: 4.8, IQR: 7.4)." (PMID 38235139, 2023). "ROC curve for diagnosing septic shock indicated an area under the curve (AUC) of 0.881 for presepsin (vs. 0.690, 0.583, and 0.527 for PCT, CRP and WBC, respectively)." (PMID 34641833, 2021). "The univariate Cox analysis indicated that the presence of septic shock, baselines levels of SOFA, SAPS III score, lactic acid, CRP, and AFR were six potential prognostic factors for septic patients." (PMID 32454793, 2020). "Other factors including septic shock, ARDS, day 1 levels of IL-1β, IL-6, IL-8 and CRP, and day 1 SOFA and APACHE II scores, were also predictive of 60-day mortality." (PMID 28542440, 2017). "We believe that, in patients with septic shock or MODS, the stimulus inducing CRP production lasts longer." (PMID 17598889, 2007). "However, the laboratory findings showed significantly lower platelet counts and hemoglobin levels as well as higher CRP, PCT, NRBC, lactic acid, ALT, CK-MB, urea nitrogen, and APTT levels in the septic shock group (P < 0.05)." (PMID 40895306, 2025). "Finally, these biomarkers were compared with CRP, procalcitonin, lactate, APACHEE II, and SOFA, which are used in daily practice, and it was investigated which of them best predicts mortality in septic shock." (PMID 37592204, 2023). "Patients with septic shock also presented with higher levels of traditional inflammatory indicators including PCT (30.22 ng/mL vs 1.00 ng/mL, P=0.0002) and CRP (155.0 mg/L vs. 111.5 mg/L, P=0.0436) than those in patients without septic shock." (PMID 35967346, 2022). "The AUC to discriminate septic shock was 0.80 for IL-6 (95% CI, 0.71–0.89; P < 0.001), 0.70 for PTX3 (95% CI, 0.60–0.81; P < 0.001), 0.73 for PCT (95% CI, 0.63–0.83; P < 0.001), and 0.53 for CRP (95% CI, 0.42–0.65; P = 0.603)." (PMID 31718563, 2019). "The early prognostic value of CRP and PCT in septic shock cases that received protocol-driven resuscitation bundle therapy at emergency departments (EDs) remains unclear." (PMID 31036824, 2019). "The patients with septic shock had lower vitamin C concentrations and higher C-reactive protein concentrations than the non-septic patients (P < 0.05)." (PMID 29228951, 2017). "We compared PTX3, procalcitonin and C-reactive protein in septic shock versus nonshock patients and in amputated versus nonamputated patients using the Mann-Whitney U test." (PMID 26880104, 2016). "The septic shock patients had lower neutrophils and lymphocytes counts, higher plasma concentrations of C-reactive protein and procalcitonin as compared with non-septic patients." (PMID 20156359, 2010). "At baseline (time = 0 h), patients with septic shock had 2.4-fold higher C-reactive protein concentrations (254 ± 121 mg/L) than non-septic patients (105 ± 84 mg/L; LMEM, z = 4.4, P < 0.001) and remained higher than non-septic patients for the first 48 h (LMEM, z = 5.6–3.9, P < 0.001–0.04)." (PMID 29228951, 2017). "Particularly, in septic shock patients the group of non-survivors showed higher SOFA score, higher lactate levels and/or acute reactant levels such as PCT and CRP." (PMID 38235139, 2023). "There were significant differences in age, occurrence of septic shock, SOFA score, initial lactate levels, procalcitonin levels, and C-reactive protein (CRP) levels between non-survivors and survivors." (PMID 33572578, 2021). "In a prospective study with 112 patients with septic shock, baseline PTX3 levels were an independent predictor of 28-day mortality, unlike CRP and PCT." (PMID 33301518, 2020).
migraine (73 papers, 2011 to 2026). "A review of 12 studies and a meta-analysis of six case-control studies suggests an association between elevated blood CRP or hs-CRP concentrations and migraine." (PMID 41402545, 2025). "Multivariate regression models were used to assess associations between hs-CRP and migraine after adjusting for age, sex, body mass index, and smoking status." (PMID 41402545, 2025). "Like CRP, high levels of fibrinogen have been associated with migraines, supporting the role of inflammation in migraine development." (PMID 38535055, 2024). "Increased risk of migraine (RR 1.46, 95% CI 1.05–2.04) was found in the highest hs-CRP levels group compared to the lowest group." (PMID 37277733, 2023). "It would be interesting for future research to investigate if the association of CRP with migraine also differs between men and women." (PMID 37277733, 2023). "An important inflammation marker that was suggested to be linked to migraine is C-reactive protein (CRP)." (PMID 37277733, 2023). "One possible explanation for the discrepancy in the association between CRP levels and migraine is the difference in the BMI distribution of the participants." (PMID 36313504, 2022). "Since systemic inflammation can contribute to an additional risk of cardiovascular disorder, increased CRP levels in migraine cases have been used to explain the relationship between migraine and cardiovascular diseases." (PMID 36313504, 2022). "Poisson regression was used to evaluate the associations between hs-CRP levels and risk ratios (RRs) of migraine, and precision of the estimates was assessed by 95% confidence interval (CIs)." (PMID 32503410, 2020). "In contrast with the present study, the Reykjavik study reported that CRP levels were similar in migraine patients and control subjects; vascular risk factors and concomitant disease were not eliminated, and the mean age of participants was 55 years." (PMID 25595197, 2015). "The association of CRP level with migraine has been shown in small case–control studies of migraine with vascular risk factors and a large prospective cohort study of women aged > 45 years." (PMID 25595197, 2015). "It was shown that vigorous physical activity was protective against chronic neck, back, and hip pain, as well as migraine, but this association was significantly blunted among individuals with elevated BMI and high CRP, underscoring the modifying role of systemic inflammation on pain pathways." (PMID 41257114, 2025). "Interestingly, a large health study investigated the influence of high-sensitive CRP (hs-CRP) at baseline on the risk of developing (chronic) migraine 11 year later." (PMID 37277733, 2023). "In the analyses adjusting for age and gender, participants with hs-CRP levels between 10.00–20.00 mg/l had increased risk of developing migraine (RR = 1.53, 95% CI 1.10–2.14), migraine with aura (RR = 1.67, 05% CI 1.01–2.76), and chronic migraine (RR = 3.43, 95% CI 1.38–8.52)." (PMID 32503410, 2020). "However, a potential causal relationship between hs-CRP and migraine cannot be evaluated in cross-sectional studies." (PMID 32503410, 2020). "In the multivariate analyses, adjusting for age and sex, elevated hs-CRP was associated with any headache (OR 1.11, 95% CI 1.05–1.17), migraine (OR 1.23, 95% CI 1.13–1.34), MA (OR 1.26, 95% CI 1.13–1.40), MO (OR 1.17, 95% CI 1.03–1.32), and other headache (OR 1.08, 95% CI 1.02–1.14)." (PMID 31558164, 2019). "The aim of this study is to examine differences in serum levels of inflammatory molecules, including PGE2, LXA4, CRP, and fibrinogen, between migraine patients and healthy controls, as well as whether these molecules have associations with the clinical features of migraines." (PMID 38535055, 2024). "In migraine, elevation of CRP may be caused by oxidative stress, leukocyte activation, and inflammatory dilation of blood vessels, and inflammatory cytokines are increased during acute attacks of migraine and between attacks." (PMID 25595197, 2015).
migraine (continued). "Furthermore, prospective studies may establish whether measurements of CRP and oxidative parameters can identify patients with migraine at risk of CV events." (PMID 24011175, 2013). "CRP as an effect modifier for the protective effect of vigorous or moderate physical activity in neck, low back, joint pain, and migraine was explored." (PMID 40426937, 2025). "Numerous previous studies have examined the relationship between circulating CRP concentrations and migraine, but results have been incongruent." (PMID 41402545, 2025). "Included studies measured inflammatory cytokines [e.g., interleukins, TNF-α, and C-reactive protein (CRP)] and related them to migraine frequency or transformation." (PMID 41377228, 2025). "Secondary outcomes included comparisons of hs-CRP levels across migraine subgroups and between each subgroup and HCs." (PMID 41402545, 2025). "Increased focus on C-reactive protein and the dorsal root ganglia has deepened researchers’ understanding of migraine pathophysiology." (PMID 41404467, 2025). "Our stratified-adjusted analysis showed that the protective effect of physical activity is only seen when CRP serum levels are low, reducing 44% (OR 0.56) of chances in developing migraine." (PMID 40426937, 2025). "The identified associations remained significant after adjusting for age, sex, BMI, and smoking status, underscoring that elevated hs-CRP levels are independently related to migraine." (PMID 41402545, 2025). "The results showed that the serum level of RBP4 was significantly lower in migraine patients and the hs-CRP level was also significantly higher in these patients than in controls." (PMID 39539367, 2024). "We were unable to establish a causal relationship between peripheral blood levels of CRP, fibrinogen, PGE2, and LXA4 and migraine because of the case–control design of our investigation." (PMID 38535055, 2024). "This study aimed to investigate the serum levels of prostaglandin E2 (PGE2), lipoxin A4 (LXA4), and other inflammatory biomarkers (C-reactive protein, fibrinogen) in migraine patients." (PMID 38535055, 2024). "The presence of higher levels of CRP in migraine patients indicates a link between inflammation and pathogenesis." (PMID 38535055, 2024). "Among the studied proinflammatory agents, an elevated level of C-reactive protein (CRP), known as a marker of systemic inflammation, has been reported in both obese individuals and patients with migraine." (PMID 38256423, 2024). "What makes CRP levels in migraine interesting is the fact that CRP has also been established as a predictor for CVD, and there seems to be a sex difference in the relation of CRP with CVD." (PMID 37277733, 2023). "Information on cross-sectional interictal CGP levels in migraine are inconsistent but some studies have reported a cross-sectional association between elevated high sensitivity C-reactive protein (hs-CRP) and migraine." (PMID 37277733, 2023). "To date, 14 studies have reported CRP levels in individuals with migraine; however, the findings have been inconsistent." (PMID 36313504, 2022). "In studies that have compared levels of inflammatory markers in migraine patients, serum NLR, MLR, and the CRP-to-albumin ratio were higher in migraine subtypes during an attack, i.e., migraine with aura, and in patients with a family history of migraine." (PMID 36362765, 2022). "In patients with migraine, some clinical clues show an increase in CRP and alterations in T lymphocyte proportions between episodes, as well as a significant increase in leukocyte adhesion and levels of cytokines." (PMID 36295508, 2022). "Meanwhile, previous studies have found that inflammation plays an important role in the pathophysiology of migraine, and the levels of serum inflammatory cytokines, such as CRP, IL-1β, IL-6, and TNF-α are higher in migraineurs compared with healthy controls." (PMID 35493816, 2022).
migraine (continued). "The levels of some migraine biomarkers differ between episodic migraine (EM) and chronic migraine (CM), but information on C-reactive protein (CRP) levels in EM and CM is conflicting." (PMID 36313504, 2022). "Examples of elevated inflammatory biomarkers, including fibrinogen and C reactive protein (CRP), have been reported in migraine pathology." (PMID 35896985, 2022). "EM and CM present different characteristics and levels of some migraine biomarkers, but evidence of the CRP levels in EM and CM is still scarce." (PMID 36313504, 2022). "C-reactive protein levels of the 365 participants with migraine (episodic migraine or chronic migraine) by clinical characteristics and comorbidities." (PMID 36313504, 2022). "In previous studies of adults classified as overweight or obese (≥25 kg/m2), the participants in the migraine group had higher CRP levels than those in the control group, except in one study from Belgium." (PMID 36313504, 2022). "C-reactive protein levels among the 365 participants with migraine (episodic migraine or chronic migraine) by class of preventive medications." (PMID 36313504, 2022). "According to studies, CRP levels increase in patients with migraines and in women who suffer migraines with aura." (PMID 35884264, 2022). "Additional studies on CRP levels in individuals with migraine in various BMI groups will provide more information to identify the complex interaction between BMI, CRP, and migraine." (PMID 36313504, 2022). "The serum C-reactive protein, neutrophil, neutrophil/lymphocyte, monocyte/lymphocyte, and C-reactive protein /albumin ratios were higher during migraine attack periods (P < 0.05)." (PMID 35004895, 2021). "Increased levels of C-reactive protein or acute-phase reactant pentraxin 3 (PTX3) were found in the systemic circulation of migraine patients." (PMID 33671172, 2021). "Several previous studies have reported a cross-sectional association between elevated high sensitivity C-reactive protein (hs-CRP) and migraine." (PMID 32503410, 2020). "In accordance with the relationship between lymphocyte and ferritin values, compared to the phenotype with migraine characteristics, lower CRP and PCT values (on admission and worst levels) were found in patients with a phenotype with TTH features." (PMID 33391152, 2020). "Among the studied proinflammatory agents, elevated level of C-reactive protein (CRP), which is known as a marker of systemic inflammation, has been reported both in obese individuals and patients with migraine." (PMID 31726975, 2019). "Frequency of family history of migraine and mean hs-CRP levels were similar between migraine patients with or without aura and were greater in migraine patients than control subjects." (PMID 25595197, 2015). "We evaluated hs-CRP levels and the relation between hs-CRP level and WMHs in adult migraine patients." (PMID 25595197, 2015). "Several studies have found elevated levels of C-Reactive Protein (CRP), a marker of chronic low-grade inflammation, in patients with migraine." (PMID 23815568, 2013). "The combination of serum CRP and NLR has diagnostic value in identifying migraine attacks." (PMID 41799720, 2026). "Likewise, a study explored the relationship between migraine and inflammation, finding higher C-reactive protein (CRP), creatinine, and thyroid-stimulating hormone levels, and lower serum iron levels in migraine patients." (PMID 40149800, 2025). "Moreover, in the gut, immune cells and inflammatory cytokines produced, such as interleukins (IL-1, IL-6), tumor necrosis factor (TNF-α), and C-reactive protein (CRP), seem to be involved in migraine pain, worsening the severity of attacks." (PMID 39861467, 2025). "This approach offers more definitive insights into the CRP-migraine relationship." (PMID 41402545, 2025). "Curcumin, a natural NF-κB inhibitor, lowered IL-6 and CRP and IL-1β in these studies, and might thus help “cool off” the chronic inflammatory state in migraine." (PMID 41377228, 2025).